FOXC1 (forkhead box C1)
Diseases named in the same sentence as FOXC1 in open-access papers (continued):
Sharing a sentence is not in itself a finding about the gene and the disease.
triple-negative breast carcinoma (15 papers, 2013 to 2025). An invasive breast carcinoma which is negative for expression of estrogen receptor (ER), progesterone receptor (PR), and human epidermal growth factor receptor 2 (HER2). "Previous studies have indicated high NF-κB expression in triple-negative breast cancer, where it promotes tumor proliferation and migration by binding to the FOXC1 promoter region, thereby increasing FOXC1 expression." (PMID 38413558, 2024). "In triple-negative breast cancer, FOXC1 can increase cell metastasis by stimulating the transcription of CXC chemokine receptor-4 (CXCR4)." (PMID 39093497, 2024). "The potential of targeting forkhead box C1 (FOXC1) as a therapeutic approach for triple-negative breast cancer (TNBC) is promising." (PMID 38183514, 2024). "A more recent study proposed that MMP7 upregulation occurred downstream of FOXC1-dependent activation of a WNT5A-NF-κB signaling axis in triple-negative breast cancer." (PMID 30764547, 2019). "Recently, our data showed that overexpression of FOXC1 increased resistance to Doxorubicin or Paclitaxel in triple negative breast cancer cells and tumors (Data wasn’t published now)." (PMID 29552326, 2018). "Cluster 5 (light-blue) contained FOXC1, a gene with regulatory and prognostic relevance in triple-negative breast cancer." (PMID 23945349, 2013). "The goal of this study was to investigate the prognostic significance of FOXC1 expression in early-stage TNBC patients treated with standard chemotherapy and the effect of FOXC1 overexpression on the chemotherapeutic response in triple-negative breast cancer patients." (PMID 28493031, 2017). "In contrast, super-enhancers found in triple-negative breast cancer (ER−, PR−, HER2−) co-localized with the transcription factors FOXC1, MET, MYC, and ANLN." (PMID 36232979, 2022). "In particular, FOXC1 is a prognostic biomarker for BLBC, which is a form of triple-negative breast cancer for estrogen receptor (ER), progesterone receptor (PR), and human epidermal growth factor receptor 2 (HER2)." (PMID 30564302, 2018). "FOXC1 inhibited P65 degradation by increasing expression of PIN1 (a peptidyl-prolyl isomerase) and reducing expression of SOCS1 (suppressor of cytokine signaling 1) in triple negative breast cancer cells." (PMID 29552326, 2018). "The median DFS was 19 months for the FOXC1-positive triple-negative breast cancer, and 32 months for the FOXC1-negative patients." (PMID 28493031, 2017). "Interestingly, the same laboratory recently reported in unrelated studies of triple negative breast cancer FOXC1-dependent activation of non-canonical WNT signaling, a pathway also thought to contribute to CSC phenotypes." (PMID 30764547, 2019).
colorectal cancer (13 papers, 2019 to 2025). A primary or metastatic malignant neoplasm that affects the colon or rectum. "FOXC1 exhibits an enhanced expression in colorectal cancer; it directly binds to the promoter region of the FBP1 gene and inhibits transcriptional activity, promoting colorectal cancer growth by enhancing the Warburg effect." (PMID 40100307, 2025). "In colorectal cancer, FOXC1 directly binds to the promoter region of the FBP1 gene and negatively regulates its transcriptional activity, whereas, AF9 reduces fbp1 transcription by targeting the FBP1 promoter through recognition of H3K9ac." (PMID 40100307, 2025). "FOXC1 enhances cell growth and reduces lactate generation and glucose usage in colorectal cancer by suppressing FBP1 expression." (PMID 39093497, 2024). "This in turn promotes ubiquitin-mediated degradation of FOXC1, rendering it unable to activate the transcription of downstream molecules, and thus blocking the proliferation and metastasis of colorectal cancer cells." (PMID 35936754, 2022). "FOXC1 is overexpressed and promotes colorectal cancer metastasis by activating the expression of ITGA7 and FGFR4." (PMID 34957298, 2021). "We identify a deletion causing FOXC1 to gain an eQTL and enhancer in pancreatic cancer, and a duplication resulting in a gain of an eQTL for BCL6 in colorectal cancer." (PMID 34257393, 2021). "Another research has indicated FOXC1 can promote colorectal cancer cell proliferation by enhancing the Warburg effect." (PMID 34082653, 2021). "In this study, we demonstrated a novel chemoresistance mechanism in colorectal cancer by performing in vitro and in vivo experiments that decreased the expression of miR-31-5p and FOXC1, which was found to be a transcription factor of miR-31-5p." (PMID 31623173, 2019). "FOXC1 promotes the proliferation of colorectal cancer cells by inducing Warburg effects." (PMID 35096062, 2022). "Although the detailed mechanisms remain unclear, USP28 was also reported to promote aerobic glycolysis of colorectal cancer by increasing stability of Forkhead Box C1 (FOXC1)." (PMID 35307036, 2022). "Recently, an increasing number of studies have shown that the expression of FOXC1 in many human malignant tumors results in a change in the expression of a series of target genes, which regulate the proliferation, migration, and invasion of tumor cells in colorectal cancer." (PMID 34957298, 2021). "The expression of FGFR4 is also regulated by forkhead box C1 (FOXC1), which directly targets FGFR4, promotes its transcription, and drives metastasis of colorectal cancer cells." (PMID 37750089, 2023). "Aberrant expression of FOXC1 and activation of the FOXC1-p38-MAPK loop promotes tumor metastasis in colorectal cancer (CRC)." (PMID 34540690, 2021). "Due to its decreased level, FOXC1 can promote the transcription of U2AF2 and enhance the biogenesis of circMAPK14, forming a positive feedback mechanism to enhance the inhibitory effect of this peptide on the proliferation and metastasis of colorectal cancer." (PMID 35936754, 2022).
Dandy-Walker malformation (12 papers, 2014 to 2025). "Meanwhile, mutations in Foxc1 in humans are often related with autosomal dominant diseases as the Axenfeld-Rieger and Dandy Walker syndromes." (PMID 32431614, 2020). "Another transcription factor, FOXC1, also associated with Dandy-Walker syndrome has been previously shown to be associated with risk of all types of ischemic stroke and with stroke severity." (PMID 32963231, 2020). "More recently, FOXC1 mutations were linked to Dandy-Walker syndrome, a group of disorders characterized by cerebellar defects and a variable set of craniofacial, cardiac and limb abnormalities." (PMID 30764547, 2019). "Abnormalities in the posterior cranial fossa, including Dandy-Walker malformation, mega-cisterna magna and cerebellar vermis hypoplasia have also been associated with homozygous FOXC1 mutations." (PMID 28344652, 2017). "Point mutations and deletions of FOXC1 have been shown to play a major role in the formation of Dandy-Walker malformations." (PMID 27087860, 2016). "Loss of Foxc1 is associated with Dandy-Walker malformation, the most common human cerebellar malformation characterized by cerebellar hypoplasia and an enlarged posterior fossa and fourth ventricle." (PMID 25513817, 2014). "Here we have demonstrated that the pathogenesis underlying Foxc1-dependent Dandy-Walker malformation, a major human neurodevelopmental disorder, is caused by loss of SDF1α-Cxcr4 mediated cerebellar radial glial proliferative and migrational scaffold function." (PMID 25513817, 2014). "Loss of Foxc1 is associated with Dandy-Walker malformation, the most common congenital malformation of the human cerebellum." (PMID 25513817, 2014). "FOXC1 loss contributes to Dandy-Walker malformation (DWM), a common human cerebellar malformation." (PMID 28092268, 2017). "Specifically, it is unknown what role non-coding mutations around the FOXC1/GMDS locus might play in developmental disorders such as Dandy-Walker syndrome." (PMID 26382291, 2016). "The disproportionate mouse cerebellar phenotypes we report here with loss of Foxc1 and Cxcr4 beautifully model the CNS phenotype of Dandy-Walker malformation patients, where the cerebellum is disproportionately diminished in size and altered in morphology relative to other CNS structures." (PMID 25513817, 2014). "One contributing factor to Dandy-Walker malformation is the loss of a protein called Foxc1." (PMID 25513817, 2014). "As the most common congenital disorders of cerebellum, affected individuals of Dandy-Walker syndrome were often detected with duplications or deletions within the Foxc1 gene." (PMID 32431614, 2020). "Previous studies of 6p25.3 deletions have demonstrated that FOXC1 is essential for normal cerebellar development, with affected patients exhibiting a spectrum of posterior fossa anomalies ranging from vermian hypoplasia to cystic changes resembling Dandy-Walker malformation." (PMID 41487851, 2025).
melanoma (11 papers, 2013 to 2025). A malignant, usually aggressive tumor composed of atypical, neoplastic melanocytes. "For instance, FOXC1 has been implicated in the regulation of cell proliferation and migration in various cancers, including melanoma." (PMID 40066251, 2025). "FOXC1 overexpression caused by hypomethylation of FOXC1 gene promoted proliferation, migration and invasion of melanoma cells." (PMID 29552326, 2018). "In conclusion, our results show that there is high FOXC1 expression in melanoma and that FOXC1 expression was associated with methylation level of FOXC1 gene." (PMID 27533251, 2016). "FOXC1 was associated with progress and prognosis of melanoma." (PMID 27533251, 2016). "Also, FOXC1 expression was associated with disease progression and poor prognosis of melanoma." (PMID 27533251, 2016). "In cervical cancers and melanoma, it was shown that FOXC1 influences cell proliferation, migration, and invasion through PI3K/AKT signaling pathway." (PMID 29976975, 2018). "FOXC1 play an important role in melanoma cells, such as invasion, migration and proliferation, colony formation and growth in 3D Matrigel." (PMID 29552326, 2018). "In particular, in melanoma cells and tissues, the promoter region of the family member FOXC1 is hypomethylated compared to normal tissues and this leads to upregulation of its expression." (PMID 29137406, 2017). "Accordingly, hypomethylating treatment of the M219 and M15 melanoma cell lines upregulated FOXC1 protein expression." (PMID 29137406, 2017). "Overexpression of FOXC1 increased tumorigenesis function of melanoma cells while knockdown of FOXC1 reduced tumorigenesis function of melanoma cells." (PMID 27533251, 2016). "FOXC1 was not only overexpressed in melanoma cell lines, but also overexpressed in melanoma tissues." (PMID 27533251, 2016). "To assess if FOXC1 promotes tumorigenesis of melanoma, we performed colony formation assay in Soft Agar and 3D matrigel culture." (PMID 27533251, 2016). "FOXC1 was closely correlated with progress and prognosis of melanoma and played an important role in melanoma." (PMID 27533251, 2016). "Our study also found that FOXC1 induced expression of MST1R and exerted function by MST1R/PI3K/AKT pathway, and that FOXC1 expression was associated with progress and prognosis of melanoma." (PMID 27533251, 2016). "It was shown that there are rich CpG islands (752bp) in the promoter region of FOXC1 gene and that there was very low methylation level of FOXC1 gene in TCGA melanoma." (PMID 27533251, 2016). "To explore the function of FOXC1 in melanoma cell lines, we transfected M219 cells which have low FOXC1 expression with FOXC1-myc-flag and Wp-0614 cells which have high FOXC1 expression with FOXC1 shRNAs." (PMID 27533251, 2016). "MST1R expression was knockdowned by MST1R siRNAs in FOXC1 overexpression melanoma cells and proliferation, migration and invasion of cells were significantly reduced." (PMID 27533251, 2016). "Our study firstly showed that alteration of FOXC1 was amplified in melanoma and even more high than most kind cancers and that FOXC1 was overexpressed in melanoma cells and tissues." (PMID 27533251, 2016). "Overexpression of FOXC1 promoted proliferation, migration, invasion, colony formation and growth in 3D Matrigel of melanoma cells." (PMID 27533251, 2016). "Taken together, these results suggested that the MST1R/PI3K/AKT pathway was activated in FOXC1 overexpression melanoma cells." (PMID 27533251, 2016). "We suggest that FOXC1 is a potential prognostic biomarker for treating melanoma and predicting outcome of patients." (PMID 27533251, 2016). "We showed that FOXC1 level was increased in melanoma cells and tissues and correlated with hypomethylation of the FOXC1 gene." (PMID 27533251, 2016). "In the current study, we showed that FOXC1 was highly expressed in the melanoma cell lines and tissues, that the methylation level of FOXC1 in melanoma is low." (PMID 27533251, 2016).
melanoma (continued). "Similarly, with regard to melanoma, there is a single publication that reports FOXC1 to have prognostic significance in advanced Stage III or Stage IV melanoma in terms of distant metastasis-free survival." (PMID 34540690, 2021). "FOXC1 exerted functional roles by activating the MST1R/PI3K/AKT pathway in melanoma." (PMID 29552326, 2018). "FOXC1 expression can be used as a biomarker in melanoma patient." (PMID 29552326, 2018). "Overexpression of FOXC1 led to resistance of melanoma cells to BRAF inhibitor PLX4032." (PMID 29552326, 2018). "All results suggest that FOXC1 may be used as a theranostic biomarker to treat melanoma and predict the progression of cutaneous melanoma." (PMID 27533251, 2016). "Increase of P65 and phosph-P65 expression may promote proliferation, migration and invasion of FOXC1 overexpression melanoma cells." (PMID 27533251, 2016). "Altogether, FOXC1 expression was related with progression of melanoma." (PMID 27533251, 2016). "In this study, we investigated the expression and function of FOXC1 in melanoma." (PMID 27533251, 2016). "All in all, these results supported that FOXC1 promotes aggressive character of melanoma cells." (PMID 27533251, 2016). "Results showed that alternation of FOXC1 was amplified in melanoma." (PMID 27533251, 2016). "That is the first report about methylation of FOXC1 gene in melanoma." (PMID 27533251, 2016). "Because the MDA-MB-435 cells originated from melanoma, FOXC1 and JunB might be more functionally active in MDA-MB-435 cells than in HeLa cells." (PMID 24815916, 2014). "FOXC1 may be used as a biomarker for diagnosis or predicting prognosis in melanoma." (PMID 27533251, 2016). "In cervical cancers and melanoma, it was shown that FOXC1 increased MST1R and activated the PI3K/AKT pathway to drive invasion and migration in melanoma cells." (PMID 34540690, 2021). "Ectopic FOXC1 expression induced MST1R expression and promoted migration and invasion of melanoma cells by activating the MST1R/PI3K/AKT pathway." (PMID 29552326, 2018). "All these results suggested that FOXC1 activated MRT1R /PI3K/AKT pathway and exerted function via the pathway in melanoma." (PMID 27533251, 2016). "Our findings indicate FOXC1 acts via the MSTR1/PI3K/AKT pathway, and its expression is related to disease progression and predicts a poor prognosis in melanoma patients." (PMID 27533251, 2016). "The majority (except FOXC1 and LEF1) was also found upregulated in the SP of the melanoma cell line." (PMID 24098529, 2013). "Other than that, ROR1, FOXC1, MIF, TGFβ, lncRNA SNHG17, MIAT, MHENCR, OR3A4 and H19 regulate proliferation, progression, migration, invasion, metastasis or EMT-like transition though PI3K/AKT pathway in melanoma cells." (PMID 32333246, 2020). "This set of genes included forkhead box C1 (FOXC1), keratin 14 (KRT14), cyclin E1 (CCNE1), melanoma inhibitory activity (MIA) and secreted frizzled-related protein 1 (SFRP1), while expression of CDCA1 and MELK, (neither of which were detectable in MCF7), did not change following SOX11 depletion." (PMID 26894864, 2016). "Taken together, these studies supported the finding that therapeutic targeting of the EGFR/FOXC1/NFκB pathway and PI3K/AKT/mTOR in BLBC, PI3K/AKT/HIF-1α/FOXC1 axis in HCC and MST1R/PI3K/AKT in cervical cancers, melanoma and pancreatic cancers, may provide effective modalities for treatment." (PMID 34540690, 2021). "However, there is no report on the clinicopathologic significance of FOXC1 in melanoma, and the role played by FOXC1 in melanoma has not yet been determined." (PMID 27533251, 2016).
Axenfeld-Rieger anomaly (10 papers, 2005 to 2025). "Mutations in PITX2 (4q25) and FOXC1 (6p25), as well as cytogenetic abnormalities involving these loci, have been found in a wide variety of phenotypes that share features with Axenfeld-Rieger anomaly." (PMID 18471320, 2008). "As in patients carrying mutations in PITX2 and FOXC1, TGFβ signal inactivation in NC cells leads to ocular defects characteristic of the human disorder Axenfeld-Rieger's anomaly." (PMID 16403239, 2005). "Ocular expression of Pitx2 and Foxc1, which when mutated can cause Axenfeld-Rieger's anomaly, is TGFβ-dependent, suggesting that both transcription factors are involved in mediating TGFβ signaling in ocular cells during development." (PMID 16403239, 2005). "In human Axenfeld-Rieger's anomaly, mutations have been found in the genes encoding the transcription factors FOXC1 and PITX2." (PMID 16403239, 2005). "In humans, hypomorphic and overactivating mutations in either gene leads to Axenfeld-Rieger's anomaly, and mutation of either Foxc1 or Pitx2 in mice results in defective anterior eye-segment formation, similar to that seen in human Axenfeld-Rieger's anomaly." (PMID 16403239, 2005). "A forkhead box C1 (FOXC1) is considered to be a cause for primary congenital glaucoma, autosomal dominant iridogoniodysgenesis anomaly and Axenfeld-Rieger anomaly." (PMID 24885071, 2014).
cervical carcinoma (10 papers, 2016 to 2025). A carcinoma arising from either the exocervical squamous epithelium or the endocervical glandular epithelium. "have proposed that miR-374c-5p exercised its functionality by targeting the FOXC1 3′ untranslated region (3′ UTR) and inhibiting FOXC1 expression, which underlines the vitality of miR-374c-5p in regulating cervical cancers by targeting FOXC1." (PMID 32199127, 2020). "A previous study found that cervical cancer derived cell line, Hela cells, lost FOXC1 gene expression due to gene mutation." (PMID 27907090, 2016). "Western blot assay showed the increase of FOXC1 levels within cultured NB cell lines, prostate cancer PC-3 cells, and cervical cancer HeLa cells, when compared to those in embryonic kidney HEK293 cells." (PMID 40416363, 2025). "Extracellular signal-regulated kinase 1/2 (ERK1/2) induces S272 phosphorylation and prolongs half-life of FOXC1 protein in cervical cancer, while SUMOylation of FOXC1 inhibits its transcriptional activity." (PMID 40416363, 2025). "hsa-miR-374c-5p plays a crucial role in the invasion and migration of cervical cancer by acting on the Foxc1/snail pathway." (PMID 35279104, 2022). "In contrast, data regarding the prognostic impact of FOXC1 expression in cervical cancer is more developed." (PMID 34540690, 2021). "FOXC1 is a promising prognostic biomarker in cervical cancer and further studies should be performed to better delineate its clinical utility in this regard." (PMID 34540690, 2021). "Additionally, miR-138-5p can directly target FOXC1 to regulate the invasion and migration of cervical cancer." (PMID 34957298, 2021). "In cervical cancer, overexpression of miR-374c-5p can inhibit the expression of FOXC1." (PMID 34957298, 2021).
prostate carcinoma (10 papers, 2017 to 2026). A carcinoma that arises from epithelial cells of the prostate gland. "The role FOXC1 plays in prostate cancer progression is unknown, but FOXC1 expression may be linked to androgen receptor levels." (PMID 31478829, 2019). "Additionally, c-Fos upregulates downstream effectors, including FOXC1 and SOX2, driving neuroendocrine differentiation in prostate cancer." (PMID 42225654, 2026).